SHISA4 (shisa family member 4)
Synonyms: C1orf40; TMEM58; hShisa4
Tractability: Antibody: UniProt predicts a signal peptide or a membrane-spanning region. PROTAC: its protein half-life has been measured.
Gene: Protein-coding gene on chromosome 1 (201,888,679 to 201,892,587, forward strand). Ensembl gene ENSG00000198892.
Subcellular location: Membrane
Gene Ontology:
Molecular function: protein binding
Cellular component: membrane
Genetic constraint (gnomAD): Loss-of-function variants: 16 observed, 24.51 expected, observed/expected ratio (o/e) 0.65, 90% interval 0.44 to 0.99. The upper end of that interval is the gene's LOEUF score, 0.99, which puts it in group 4 of 6, group 1 being the genes least tolerant of losing a copy. Missense variants: 238 observed, 253.2 expected, observed/expected ratio (o/e) 0.94, 90% interval 0.85 to 1.05. Synonymous variants: 106 observed, 101.6 expected, observed/expected ratio (o/e) 1.04, 90% interval 0.89 to 1.23.
Homologues: Orthologues: chimpanzee SHISA4 (99% identical), rabbit SHISA4 (94% identical), pig SHISA4 (93% identical), mouse Shisa4 (92% identical), rat Shisa4 (91% identical), macaque SHISA4 (90% identical), guinea pig SHISA4 (89% identical), dog SHISA4 (86% identical), tropical clawed frog shisa4 (51% identical), zebrafish shisa4 (48% identical). Paralogues in human: SHISA2 (25% identical), SHISA3 (23% identical), SHISAL1 (20% identical), SHISAL2A (18% identical), SHISAL2B (14% identical).
Diseases named in the same sentence as SHISA4 in open-access papers:
SHISA4 is named in the same sentence as 8 diseases in open-access papers, as found by Europe PMC text mining. Sharing a sentence is not in itself a finding about the gene and the disease. The quoted sentences say what the papers report.
Alzheimer disease (1 paper, 2023). A progressive, neurodegenerative disease characterized by loss of function and death of nerve cells in several areas of the brain leading to loss of cognitive function such as memory and language. "Finally, SHISA4, a component of membranes, was another gene downregulated in APOE4 carriers that has recently been found to be downregulated in mildly cognitively impaired and AD individuals in blood expression analyses using Alzheimer’s Disease Neuroimaging Initiative data." (PMID 37438770, 2023).
asthma (1 paper, 2022). "Commonly downregulated to PTSD and severe asthma were ORMDL3 (2.2E-2, 1.9E-3, 2.7E-3, 3.9E-3), PTP4A3 (2.6E-3, 2.3E-2, 4.5E-3, 5.2E-3), SHISA4 (1.1E-2, 4.4E-2, 9.8E-3, 6.2E-3), and TPPP3 (2.2E-2, 1.1E-2, 3.1E-3, 2.7E-2)." (PMID 36206293, 2022).
bacterial meningitis (1 paper, 2024). Inflammation of the membranes surrounding the brain and spinal cord due to a bacterial infection. "In bacterial meningitis patients, 8 co-expression relationships were constructed between 8 mRNAs (ACBD7, OR52K2, GPR68, SHISA4, KIF5C, OR52P2P, OR51R1P, and CCR5) and 1 lncRNA." (PMID 38347610, 2024).
colorectal cancer (1 paper, 2023). A primary or metastatic malignant neoplasm that affects the colon or rectum. "SHISA4 is a member of the Wnt pathway that has been previously linked to 5FU resistance in colorectal cancer." (PMID 36675023, 2023).
SHISA4 also shares sentences with these, for which no sentence is quoted: breast carcinoma (1 paper); colon cancer (1); colorectal adenoma (1); tumor (1).